RAB1A (RAB1A, member RAS oncogene family)
Diseases named in the same sentence as RAB1A in open-access papers (continued):
Sharing a sentence is not in itself a finding about the gene and the disease.
tumor (60 papers, 2005 to 2025). "Our results indicated that Rab1A expression was obviously linked to the depth of tumor invasion, lymph node invasion, venous invasion, and TNM staging." (PMID 33214609, 2020). "Additionally, the mRNA expression of Rab1A was closely associated with that of IL-4Rα in GC tumor tissues (P < 0.001)." (PMID 37117331, 2023). "Above results suggest that Rab1A is closely associated with radiosensitivity and tumor metastasis." (PMID 33068388, 2020). "And high expression Rab1A level was marginally associated with deeper tumor invasion (P = 0.053)." (PMID 33068388, 2020). "For instance, circ_002136 promotes HCC progression through the miR-19a-3p/RAB1A axis, while tumor-derived exosomal circUHRF1 induces NK cell exhaustion and PD-1 resistance." (PMID 40299340, 2025). "Consistent with RAB1A’s role in promoting tumor malignancy, RAB1A overexpression significantly stimulated GC cell growth." (PMID 39771598, 2024). "Taken together, these findings demonstrated that RAB1A is critical for C118P’s anti-tumor activity in GC cells, highlighting its role as a key therapeutic target." (PMID 39771598, 2024). "Our results showed that the mRNA expression of Rab1A was closely related to the IL-4Rα mRNA expression in GC tumor tissues." (PMID 37117331, 2023). "The PERMANOVA analysis revealed that the IHC scores of Rab1A and IL-4Rα significantly differed between tumor and normal tissues (P = 0.001)." (PMID 37117331, 2023). "The high abundance of exosomal circ_002136 targeted miR-19a-3p/RAB1A pathway in cancer cells to disrupt the stable microenvironment inside the tumor and exacerbate the malignant process of HCC tumors." (PMID 36476239, 2022). "The combination of shSGOL2 with RAB1A overexpression had similar inhibitory effects on tumor growth and reversed the shSGOL2 effects on proliferation ability." (PMID 36566018, 2022). "The results showed that the expression level of Rab1A in CRC tumor tissues was higher compared with that in the normal matched tissues (P < 0.01)." (PMID 34376787, 2021). "High Rab1A expression was markedly related to pathological large tumor size (χ2 = 12.289, P < 0.001), LNM (χ2 = 8.279, P = 0.004), and advanced TNM stage (χ2 = 17.467, P < 0.001)." (PMID 34376787, 2021). "We performed IHC of collected CRC tissue samples and found that Rab1A expression markedly increased in tumor tissues in comparison to the normal tissues (P < 0.01)." (PMID 34376787, 2021). "In the present work, our data confirmed increased expression of Rab1A in human CRC tumor tissues in comparison to the normal tissues." (PMID 34376787, 2021). "In the present study, we found that Rab1A expression was significantly upregulated in CRC tissues and increased Rab1A expression correlated with tumor size, lymph node metastasis (LNM) and tumor-node-metastasis (TNM) stage of CRC patients." (PMID 34376787, 2021). "Further IHC analysis revealed that compared to those with tumor size < 5 cm, Rab1A expression was higher in tumors ≥ 5 cm (P < 0.001)." (PMID 34376787, 2021). "In different clinical subgroups, we found that Rab1A expression remarkably increased in patients with deep tumor invasion (T3-4) and advanced TNM stage (stage III-IV) (All P < 0.05)." (PMID 33068388, 2020). "Many articles have reported that Rab1A was overexpressed in a variety of human cancers and involved in tumor progression and metastasis." (PMID 33068388, 2020). "Taken together, Rab1A depletion retarded GC tumor growth in mice, indicating that it acts as an oncogene in GC progression." (PMID 31527621, 2019). "Rab1A knockdown significantly abrogated GC cell growth in vitro and inhibited tumor progression in vivo, indicating a novel therapeutic target against gastrointestinal cancers." (PMID 31527621, 2019). "To further confirm any prognostic relevance of the aberrantly high levels of Rab1A in various gastrointestinal cancers, we analyzed the in situ Rab1A expression in paired tumor and adjacent normal tissues in GC patients." (PMID 31527621, 2019).
tumor (continued). "Overexpression of Rab1A promotes mTORC1 signaling and oncogenic growth in response to amino acids stimulation and therefore enhances tumor progression and invasion in colorectal cancer." (PMID 27716280, 2016). "Compared with the activated H-RASV12 oncogene, RAB1A displays stronger transforming activity as measured by cell growth, colony formation and xenograft tumor assays." (PMID 26590354, 2015). "Taken together, our data suggest that miR-15b-5p induces ERS, apoptosis, and growth inhibition by targeting and suppressing Rab1A, acting as a tumor suppressor gene in HCC." (PMID 26023735, 2015). "Among the tumours examined, 53 of 54 cases (98%) had a Rab1A-immunoreaction in the cytoplasm of the tumour cells." (PMID 15870709, 2005). "Overall, our findings suggested that RAB1A knockdown attenuated tumor development, indicating that RAB1A might have potential as a therapeutic target to inhibit PCa development." (PMID 41050665, 2025). "Collectively, these results demonstrated that the anti-tumor activities of C118P against GC cells were attenuated following RAB1A knockdown, reflecting that C118P exerts its anti-tumor effects in GC cells via targeting RAB1A." (PMID 39771598, 2024). "However, most existing studies on RAB1A are regarding its role in tumours, with hardly any studies on its role in NAFLD." (PMID 38436022, 2024). "Finally, the qPCR helped explore the Rab1A/IL-4Rα mRNA expression in 24 tumor and normal tissue cases, displaying heatmap." (PMID 37117331, 2023). "Finally, qPCR helped investigate the Rab1A/IL-4Rα mRNA expression in 24 tumor and normal tissue cases." (PMID 37117331, 2023). "In addition, RAB1A mRNA appeared high abundance expression in both HCC tumor tissues and cells, with an expression trend opposite to miR-19a-3p." (PMID 36476239, 2022). "Furthermore, tumor tissues with deeper invasion (T3-4) exhibited higher Rab1A expression than those with T1-2 (P < 0.05)." (PMID 34376787, 2021). "In addition, Rab1A expression levels were also positively correlated with the tumor-node-metastasis (TNM) stage of CRC patients (P < 0.001)." (PMID 34376787, 2021). "A possible explanation for these reported contradictory functions of Rab1A protein may be due to its distinct roles in specific tumor types and/or other oncogenic events." (PMID 33068388, 2020). "We found that Rab1A expression was closely related to FoxM1 expression in tumor tissues, whereas no obvious expression association in normal tissues was observed." (PMID 33214609, 2020). "Results revealed that Rab1A expression was positively associated with FoxM1 expression in TNM stage III, indicating that Rab1A and FoxM1 might have promoted tumor progression." (PMID 33214609, 2020). "To validate the database findings, we analyzed in situ Rab1A expression in the tumor and para-tumor tissues of GC patients, and not only observed aberrantly high levels of Rab1A in the former, but also a significant correlation between its overexpression and worse 5-year survival." (PMID 31527621, 2019). "Furthermore, Rab1A was overexpressed in the gastrointestinal tumor tissues compared to the para-tumor tissues." (PMID 31527621, 2019). "Recently, lots of studies indicated that RAB1A plays important roles in tumor progression." (PMID 29301870, 2018). "Large tumors and late T stage tumors consistently displayed higher Rab1A expression when compared with small tumor size and early T stage, indicating that Rab1A may promote tumor growth and progression." (PMID 27902464, 2016). "On an individual basis, Rab1A scored higher in approximately 96.67% (58/60) of tumors than in the corresponding noncancerous tissues, although Rab1A staining was remarkably variable, differing by as much as 100-fold between different tumor samples." (PMID 27902464, 2016). "Rab1A overexpression specifically enhances mTORC1 signaling, tumor invasion and progression." (PMID 26590354, 2015).
tumor (continued). "In xenograft mouse models established by injecting SK-HEP-1-Rab1A or BEL-7402-Rab1A cells into the right dorsal flanks and subcutaneously vector control cells into the left dorsal flank of the same animals, tumor burden with Rab1A overexpression is significantly larger than control tumors." (PMID 26308575, 2015). "Studies with in vitro and in vivo tumor models demonstrated that RAB1A is a potent oncogene." (PMID 26590354, 2015). "In cancers, the role of Rab1A is contentious and it could be either oncogenic or tumor suppressive." (PMID 34376787, 2021). "Besides, other Rab GTPases, such Rab1a and Rab31 have also been reported to affect mTOR pathway in tumor, but it is unclear whether these effects are achieved by the membrane transport of Rab GTPases." (PMID 34141705, 2021). "Univariate analysis indicated that differentiation degree, venous invasion, neural invasion, depth of tumor invasion, LNM, TNM stage, and Rab1A expression were closely related to poor prognosis (P < 0.05)." (PMID 37117331, 2023). "HSC70 inhibition downregulates Rab1A expression, while Rab1A inactivation leads to cell death via inhibition of autophagosome formation, suggesting that HSC70 promotes tumor survival by stabilizing Rab1A." (PMID 35127545, 2022). "We also found that Rab1A expression level was further increased in tumors with positive LNM, larger tumor sizes, deeper invasion and advanced TNM stage." (PMID 34376787, 2021). "In the current study, we confirmed the overexpression of Rab1A in NPC samples and its positive correlation with tumor metastasis of NPC patients." (PMID 33068388, 2020). "Rab1A expression was moderately higher in ESCA, STAD, COAD, and READ tumor tissues compared to normal tissues; however, this difference was not significant (P > 0.05)." (PMID 33214609, 2020). "Consistent with previous results, in the present study, we found that the addition of RAB1A in the context of miR-19a-3p overexpression enhanced the malignant phenotype of HCC cells, suggesting that miR-19a-3p regulates tumor cell progression in a RAB1A-dependent manner." (PMID 36476239, 2022). "To explore whether Rab1A plays a role in CRC, we first set out to determine Rab1A expression in CRC tumor tissues and surrounding normal tissues." (PMID 34376787, 2021). "According to the Rab1A and FOXM1 IHC score of human CRC and adjacent normal tissues, it was illustrated as a cluster analysis diagram to demonstrate the differences in expression of the two proteins in tumor and normal tissues." (PMID 33214609, 2020). "RablA overexpression was also reported in human lung cancer, which is correlated with tumor volume and stage, but the tumorigenic function of Rab1A is not dependent on mTOR or MAPK signaling." (PMID 28316326, 2017). "In contrast to the noncancerous tissues, Rab1A was significantly highly expressed in tumor cells, while faint staining was present in stromal and lymphoid cells in paired noncancerous tissues." (PMID 27902464, 2016). "Overexpression of Rab1A is correlated with a poor prognosis and has been proposed to promote tumor progression by activating the mTORC1 signaling pathway in CRC and HCC, indicating that Rab1A might be a valuable therapeutic target for personalized therapy." (PMID 27902464, 2016). "Subgroup analysis showed that Rab1A expression was remarkably higher in TNM stages II, III, and IV compared to that in TNM stage I, which indicated that Rab1A expression might play a critical role in tumor initiation and development." (PMID 33214609, 2020). "Therefore, in this present study, we investigated the expression and clinical predictive value of Rab1A in NPC samples and assessed the potential biological functions of Rab1A in vitro, then explored the molecular basis involved in tumor metastasis and radioresistance." (PMID 33068388, 2020).
tumor (continued). "Furthermore, it indicated the body weight without tumor weight treated with Rab1A depletion was significant heavier than the control group mice, which reached an obviously difference (P < 0.05)." (PMID 31527621, 2019).
cancer (29 papers, 2014 to 2025). A tumor composed of atypical neoplastic, often pleomorphic cells that invade other tissues. "Because activation of both Rab1A and Rab1B were implicated in multiple cancer types, both should be considered when studying cancer." (PMID 36781179, 2023). "Future questions about Rab1A/B in human health would center around their association with acquired diseases associated with aging, that is, cancer and neurological disorders." (PMID 36781179, 2023). "Second, Rab1A and Rab1B were implicated in multiple human diseases that range from cancer to neurodegeneration." (PMID 36781179, 2023). "Rab1A/B was specifically implicated in cancer and neurodegenerative disease." (PMID 36781179, 2023). "In addition to this mechanistic insight, these findings are relevant to human health because both the pathways and Rab1A/B were implicated in diseases ranging from cancer to neurodegeneration." (PMID 36781179, 2023). "In any case, RAB1A has been implicated in cancer progression and poor prognosis." (PMID 32790781, 2020). "Recent studies have shown that the Rab1A proteins are also involved in regulating signal transduction and autophagy, and its aberrant expression levels are associated with proliferation, migration and drug-resistance in various cancers." (PMID 31527621, 2019). "The effect of Rab1A expression on multiple cancer-associated signaling pathways was also examined." (PMID 27902464, 2016). "Moreover, aberrant expression of Rab1A has been linked to a range of human diseases including cardiomyopathy, Parkinson's disease and cancer." (PMID 27902464, 2016). "To elucidate the potential contribution of RAB1A to the immune modulation of cancer immunoediting, we used RAB1A overexpression plasmid and GW4869, an inhibitor of exosome biogenesis to establish the experimental model." (PMID 41050665, 2025). "The overexpression of RAB1A promotes oncogenesis and makes cancer cells vulnerable to mTORC1-targeted treatment." (PMID 39771598, 2024). "RAB1A overexpression promotes cancer cell migration, invasion, and metastasis by activating JAK1/STAT6 signaling." (PMID 37370041, 2023). "The regulation of mTOR signaling by Rab1A was reported by several studies in multiple types of cancers including CRC." (PMID 34376787, 2021). "In those studies, Rab1A was shown to be a mTOR activator and an oncogene, frequently overexpressed in human cancer (55, –, 57)." (PMID 34346699, 2021). "Rab1A, as a highly conserved small guanosine triphosphatase (GTPase), plays contentious roles in different types of cancers." (PMID 34376787, 2021). "We detected significantly higher expression of Rab1A in the gastrointestinal tumor tissues compared to that in other cancer types following an in silico analysis of TGCA and GTEX databases." (PMID 31527621, 2019). "Rab1A expression was significantly higher in GC tissues compared to the para-cancer tissues in the entire patient cohort (P < 0.001), and the OS of the Rab1Ahi group was considerably lower compared to that of the Rab1Alo patients (P < 0.001)." (PMID 31527621, 2019). "Cases were divided into high and low Rab1A staining groups based on the median H score of 180 in cancer tissues." (PMID 27902464, 2016). "Consistent with the role of Rab1A in AA signaling, RAB1A overexpression renders cancer cells more reliant on AA for their growth and survival, suggesting that these cancer cells have become addictive to AA-mTORC1 signaling pathway signaling." (PMID 26590354, 2015). "Strikingly, aberrant Rab1A overexpression leads to increased rapamycin sensitivity, indicating that inappropriate activation of AA signaling is a cancer-driving event in HCC." (PMID 26308575, 2015). "To extend our proteomics findings, we next evaluated the contribution of Rab1A to cancer cell survival." (PMID 24801886, 2014). "The proteomics analysis of Hsc70 interactors identified Rab1A, which was shown to be required for cancer cell survival under stress conditions." (PMID 24801886, 2014).
cancer (continued). "Of these, we focused on Rab1A in the Ras superfamily, which is expressed at a high level in cancer cells." (PMID 24801886, 2014). "Although there were a few Hsc70 interactors common to the two different stresses, we identified Rab1A as contributing to cancer cell survival under stress conditions." (PMID 24801886, 2014). "Among the proteins identified under both serum-depleted and 5-fluorouracil-treated conditions, Rab1A was identified as an essential molecule for cancer cell survival." (PMID 24801886, 2014). "Studies have shown that the overexpression of RAB1A in cancer cells may promote autophagy progression by effecting with optic nerve protein (OPTN, an autophagy receptor)." (PMID 38436022, 2024). "Moreover, Rab1A behaved as an oncogene in various cancers, enhancing growth, metastasis, and cancer cell drug resistance." (PMID 37117331, 2023). "Recent studies indicated Rab1A, an oncogene, is aberrantly elevated in various cancers." (PMID 37117331, 2023). "Overexpression of miR-139-3p inhibited malignant cancer cell phenotypes by targeting RAB1A." (PMID 34576110, 2021). "As for Rab1 signaling pathway, studies showed that Rab1A might be an mTORC1 activator and a potential target in treating cancer progression." (PMID 32587477, 2020). "Therefore, it is of biological and clinical significance to elucidate the effect of Rab1A in cancers, especially those of the gastrointestinal system." (PMID 31527621, 2019). "Furthermore, Rab1A was associated with S6K levels in 7 cancers, with Gli1 in 2 cancers, AKT in 7 cancers, HER2 in 2 cancers, and with EGFR in 6 cancers." (PMID 31527621, 2019). "In addition, Rab1a was correlated to S6K in 7 cancers, Gli1 in 2 cancers, AKT in 7 cancers, HER2 in 2 cancers, and EGFR in 6 cancers." (PMID 31527621, 2019). "Indeed, cancer cells with high RAB1A expression are hypersensitive to rapamycin, a highly selective mTORC1 inhibitor." (PMID 26590354, 2015). "Rab1A may therefore contribute to overcoming proteotoxic insults, which allows cancer cells to survive under stress conditions." (PMID 24801886, 2014). "However, there is increasing evidence that the aberrant expression of RAB1A is involved in the development of human diseases, including cardiomyopathy, aspirin-exacerbated respiratory disease, sepsis, and, in particular, cancer." (PMID 39771598, 2024). "Rab1A and Rab1B may be oncogenes, as they are frequently dysregulated in various human cancers." (PMID 38559361, 2023). "However, it remains unclear whether Rab1A is overexpressed in common human cancers, and if so, what the significance and mechanism of Rab1A overexpression are in the pathobiology of cancer." (PMID 26308575, 2015). "The alteration frequencies in cancer cell lines were as follows: CDKN1A (4%), DNAJB9 (6%), GABARAPL1 (5%), RAB1A (1.6%), and VAMP7 (0.6%), with amplification being the most common type of alteration." (PMID 41040512, 2025). "Further studies addressing the functional role of GOLPH3 binding to RAB1A and RAB1B will provide insights on GOLPH3 function in normal and pathological conditions such as in cancer." (PMID 32790781, 2020). "In terms of its cellular effects, some studies showed that Rab1A promoted cellular proliferation, invasion and EMT process through activation of mTOR signaling in several cancers." (PMID 33068388, 2020). "Compared to other cancers, the gastrointestinal types, especially CRC, showed significantly increased expression of Rab1A." (PMID 31527621, 2019). "While RAB1A is predicted to be a novel marker for the diagnosis, treatment, and prognosis of cancer patients in clinics, there is still a lack of molecularly targeted drugs for RAB1A." (PMID 39771598, 2024). "By examining the differential expression of RagC, Rheb, RalA, Rab1A, Rab5, and Arf1 in cancer tissues (n = 369) and non-cancer controls (n = 160), we showed that RagC and Arf1 but not Rheb, RalA, Rab1A or Rab5 were significantly elevated in cancer tissues." (PMID 36267578, 2022).